CLDN3 (claudin 3)
Diseases named in the same sentence as CLDN3 in open-access papers (continued):
Sharing a sentence is not in itself a finding about the gene and the disease.
cancer (continued). "We also detected enrichment for transcripts encoding fibroblast-specific protein 1 (FSP1/S100a4), keratins Krt7, Krt8, Krt14 and Krt18 and claudins Cldn3, Cldn4 and Cldn7 in this cluster which were also enriched in epithelial/cancer cells." (PMID 32455670, 2020). "Alterations of CLDN3 gene expression have been frequently observed in several human cancers, with discordant findings about their role." (PMID 32664456, 2020). "Claudin-3, -4, and -7 are the most frequently dysregulated members of this family in human epithelial cancers and their functional importance in cancer progression to metastatic disease is well-established." (PMID 32850397, 2020). "We demonstrated the ADCC activity of h4G3 in many types of cancer cell lines according to CLDN3 expression levels." (PMID 31905631, 2019). "The ADCC EC50 of h4G3 was correlated with mean fluorescence intensity (MFI) of CLDN3 expression in various cancer cell lines, except for a few cell lines such as AsPC-1 and NCI-H684." (PMID 31905631, 2019). "This indicates its potential value as a diagnosis and for CLDN3-targeted therapy for the treatment of cancer." (PMID 31905631, 2019). "Overexpression of CLDN3 has been reported in various malignant carcinomas, and CLDN3 has emerged as a potential cancer biomarker and therapeutic target because of its surface expression pattern associated with tumorigenesis." (PMID 31905631, 2019). "We applied a hard filter to the GSMs and finally selected six genes (CLDN3, DECR2, EVA1B, NME4, NTSR1 and XPNPEP3) associated with epigenetic regulation, differentiation and cancer (Pearson’s correlation test; p-value ≤ 0.001)." (PMID 31040866, 2019). "Further, claudin-3 inhibition by small-molecule inhibitors including withaferin A, estradiol and fulvestrant, suppressed cancer stemness and combated chemoresistance, giving strong evidence for the role of claudin-3 in inducing stemness." (PMID 31861759, 2019). "Attachment of the h4G3 to the membrane of CLDN3-expressing cancer cells was observed when it was treated to the cells before fixation." (PMID 31905631, 2019). "These approaches using CPE provide proof of concept for cancer diagnosis and treatment targeting CLDN3." (PMID 31905631, 2019). "The h4G3 showed antibody-dependent cellular cytotoxicity (ADCC) according to CLDN3 expression levels in various cancer cells by the activation of FcγRIIIa (CD16a)." (PMID 31905631, 2019). "In order to verify the recognition in cancer cells, the expression of CLDN3 was confirmed, and h4G3 binding on the cell surface in various cancer cell lines was observed according to CLDN3 expression." (PMID 31905631, 2019). "The ADCC activity of h4G3 according to CLDN3 expression levels was examined in representative cancer cell lines using NK-92MI-CD16a cells." (PMID 31905631, 2019). "High CLDN3 expression is correlated with poor prognosis and survival, and CLDN3 is considered a pan-carcinoma biomarker." (PMID 31905631, 2019). "Because of its expression in various carcinomas, CLDN3 has been investigated as a therapeutic target." (PMID 31905631, 2019). "CD24 has prognostic value in survival as a marker for cancer stem cells whereas CLDN3 and CLDN4 have been shown to regulate the epithelial to mesenchymal transition." (PMID 30383866, 2018). "Previous experiments demonstrated that CPE by binding to a subset of claudins, e.g. claudin-3 and -4, killed cancer cells." (PMID 30297847, 2018). "Taken together, our data demonstrates significant CLDN3 overexpression in ADC tissues and predicts a potential correlation between CLDN3 expression and cancer progression." (PMID 28160565, 2017). "Recent studies indicated potential functions of claudin-3 on tumorigenesis and revealed that high claudin-3 expression was correlated with shorter overall survival in several cancers." (PMID 28383479, 2017). "The targeted action of CPE is mediated by binding to claudin-3 and -4, which are frequently overexpressed in cancers." (PMID 28193196, 2017).
cancer (continued). "By contrast, CPE has the advantage of specific binding to claudin-3 and -4, which is accessible at the cell surface and potentially also in the cytoplasm of cancer cells." (PMID 28193196, 2017). "Using methylated DNA immunoprecipitation coupled with DNA microarray (MeDIP-chip) analysis, we have identified that CLDN3 was preferentially methylated in cancer." (PMID 25277196, 2014). "By using genome-wide methylation profiling analysis, we identified CLDN3 as an epigenetically regulated gene in cancer." (PMID 25277196, 2014). "In observational studies, decreases in claudin-3 and -4 have been reported in GC cells at the invasive front and were found to correlate with cancer progression and metastasis." (PMID 24073219, 2013). "The mechanism of the increased claudin-3 and-4 expression in ovarian carcinoma is thought to be the result of epigenetic modifications of the claudin promoter regions in the cancer cells resulting in increased cell survival, invasion and motility." (PMID 23685873, 2013). "The toxin is especially lethal for cells expressing large amounts of claudin-3 or -4, which includes many cancer cells." (PMID 21941545, 2012). "Next, we analyzed the binding ability of CLDN3-mAb to different human cancer cells." (PMID 40057807, 2025). "The overexpression of CLDN3 can lead to a decrease in or even loss of cell–cell adhesion, resulting in the promotion of epithelial–mesenchymal transition (EMT), which is implicated in the pathophysiology of numerous types of cancers." (PMID 40564394, 2025). "Despite its widespread expression in normal epithelial cells, CLDN3 is considered an attractive drug target candidate, since it may be more accessible in cancer cells than in normal cells due to their less orchestrated cell growth." (PMID 39658782, 2024). "This discovery opens up the possibility of using CLDN3 as a targeted therapy for malignant tumors." (PMID 38534739, 2024). "Similarly, the suppression of CLDN3 in non-small-cell lung cancer decreased cancer stemness and improved chemosensitivity." (PMID 38731853, 2024). "Because mouse claudin-3 is a high-affinity CpE receptor and human claudin-3 is a moderate-affinity receptor, results from mouse models of claudin-3-expressing cancers may appear more specific and, thus, cannot be used directly to predict outcomes in humans." (PMID 35269525, 2022). "Furthermore, although the function of Cldn3 and Cldn4 is usually associated with tight junctions in normal tissues, they do not appear to have this role in tumors, suggesting a conceivable role of Cldn3 and Cldn4 in cancer progression." (PMID 35006480, 2021). "However, employment of wild‐type CPE (CPEwt) for cancer treatment is restricted to carcinomas, which express CPEwt‐binding claudins (e.g., Cldn3, Cldn4)." (PMID 31825142, 2020). "Tight junction proteins, especially claudin-3 (CLDN3), are overexpressed in various cancers." (PMID 31905631, 2019). "Therefore, h4G3 is a promising candidate for conjugation to various imaging probes and therapeutic agents, and for CAR immunotherapy for the diagnosis and treatment of CLDN3-expressing pan-carcinoma." (PMID 31905631, 2019). "Since CLDN3 is a tight junction (TJ) protein and disruption of TJ barrier could facilitate dissociated cancer cells to metastasize, we thus determine the metastatic role of CLDN3 in HCC cells by wound-healing assays and Boyden chamber matrigel invasion assays." (PMID 25277196, 2014). "Additionally, the majority of hyperplastic components were immunonegative for claudin-3, while claudin-3 positivity was observed in the majority of areas of dysplasia and carcinoma." (PMID 24765156, 2014). "However, claudin overexpression, particularly that of claudin-3 and claudin-4, has been reported in various cancers." (PMID 24009024, 2013). "In OC, CLDN3 overexpression may promote the invasion and movement of cancer cells." (PMID 38493179, 2024).
cancer (continued). "This down-regulation was due to transcriptional or post-transcriptional deregulation, given that these cancers did not possess deep deletions or mutations in claudin genes, CLDN3, CLDN4 or CLDN7, and only 5% of claudin-low cases had deep deletions in the occludin gene OCLN." (PMID 37504297, 2023). "Our observation that TGF-β1 induces nuclear CLDN3 localization in bronchiolar epithelia demonstrates that nuclear CLDN localization is not solely linked to carcinoma cells and the herein investigated example points to a role for CLDN3 in TGF-β1 signalling in bronchial epithelia." (PMID 33386991, 2021). "Therefore, we report, based on the protein expression analysis of a total of 275 patient samples, that claudin-3 (CLDN3) expression is significantly increased in ADC tissues and is associated with cancer progression, correlating significantly with the poor survival of ADC patients (p=0.041&0.029)." (PMID 28160565, 2017). "Furthermore, claudin-3 was also overexpressed in breast and prostate cancers." (PMID 28383479, 2017). "Because these receptors are highly differentially expressed in many human tumors, claudin-3 and claudin-4 may provide an efficient molecular tool to specifically identify and target biologically aggressive human cancer cells for CPE-specific binding and cytolysis." (PMID 25835384, 2015). "Interestingly, claudin-3 and -4 have been documented to have coordinate expression in several normal and neoplastic tissues and the combination is commonly found elevated in a variety of cancers." (PMID 23685873, 2013). "A dose-dependent in vitro anti-proliferative response to BsADCs was observed in the EpCAM and CLDN3 high-expressing OVCAR-3 and NCI-H1781 cancer cells." (PMID 40057807, 2025). "The membrane protein claudin-3 (CLDN3) is crucial for the formation and maintenance of tight junctions and is highly expressed in various cancers." (PMID 38415253, 2024). "Cancers with MSI were characterized by downregulation of claudin 1, claudin 3, and claudin 4 and upregulation of claudin 7 and occludin." (PMID 37998722, 2023). "We also observed differential expression of cancer-metastasis-inducing genes, such as ZEB1, MMP9, CLDN3, TWIST1 and N-cadherin, between LVI(+) and LVI(−) samples in some patients, indicating a correlation of VCAN with EMT genes in LVI(+) samples." (PMID 37108649, 2023). "Differential expression analyses comparing cancer areas of rHGP and dHGP revealed established CRC cell markers, such as FABP1, CEACAM5, CLDN3, EPCAM and S100A10 in the rHGP (Supplementary Spreadsheet 1)." (PMID 36691028, 2023). "We observed that CLDN3, CLDN4, and CLDN7 transcripts were up-regulated in most of the dysplastic or cancer cells, although these genes were also expressed in some of the intestinal cell lineages." (PMID 37196797, 2023). "Analyzing the data on the expression of claudin-3 and -4 and on the signaling pathways involved in the malignant transformation of the epithelial cells suggests that the changes in the expression of claudins may reflect triggering signaling mechanisms to contribute to cancer development." (PMID 34638619, 2021). "Clostridium perfringens enterotoxin (CPE) can be used to eliminate carcinoma cells that overexpress on their cell surface CPE receptors – a subset of claudins (e.g., Cldn3 and Cldn4)." (PMID 31825142, 2020). "CPE is regarded as a therapeutic tool for epithelial malignant tumors by utilizing the damage of CLDN4 and CLDN3." (PMID 32064037, 2020). "The dual-targeting antibodies against CLDN3 and CLDN4 have shown anti-cancer efficacy in a preventive model in which the antibody was injected on day 0 after the inoculation of cancer cells." (PMID 31905631, 2019). "Here we propose a mechanism for this effect by which miR-30a counteracts the aggressiveness and metastasis of cancer cells by increasing tight junction molecules—CLDN-1, CLDN-2, and CLDN-3—via targeting the 3′-UTR of Slug mRNA." (PMID 26918943, 2016).
cancer (continued). "These cancers are thus ideal candidates for a for a novel therapy being developed based on CPE, a toxin that specifically binds claudin-3 and claudin-4." (PMID 16836752, 2006). "Next, we constructed 15 EpCAM X CLDN3 bsAbs and tested their binding and internalization activity in OVCAR-3 and NCI-H1781 cancer cells to obtain bsAbs that could restore binding and internalization activities." (PMID 40057807, 2025). "While CPE is not specific for CLDN3 but also binds to other claudins, specific antibodies have been developed for treating cancer." (PMID 39658782, 2024). "The spatial domain 2 were enriched in the GO terms and KEGG pathways of cell differentiation, and included cell markers, such as EPCAM, KRT8, and CLDN3, which are connected with epithelial carcinogenesis, epithelial-mesenchymal transition (EMT) or cancer enhancement." (PMID 38972896, 2024). "One of the major contributing factors for the role of claudin-3 is regulation of cancer stemness and chemoresistance in non-squamous NSCLC." (PMID 31861759, 2019). "Additionally, we verified an immunophenotype comparable to human patient OSPC samples based on the expression of Claudin 3, Claudin 4, Cytokeratin 7, p16, and EMA in SCID pig carcinomas." (PMID 30723704, 2019). "Importantly, Claudin 3 and 4 expression in SCID pig carcinomas was also highly similar to the observed expression pattern in the original human carcinoma." (PMID 30723704, 2019). "The different significance level of the “new” markers as compared to KLK3/PSA (p = 1.2 × 10−16 for FLNC, 1.67 × 10−9 for CLDN3, 1.89 × 10−3 for KLK3/PSA) could indicate that these markers are more powerful for the discrimination of cancer and normal tissue." (PMID 24477410, 2014). "Furthermore, h4G3 may be suitable for cancer imaging, therapeutic agent conjugation, and CAR immunotherapy for CLDN3-positive cancer." (PMID 31905631, 2019). "To date, previously known anti-CLDN3 antibodies have not shown in vivo anti-cancer efficacy." (PMID 31905631, 2019). "CLDN3 and PSRR8 have been proven to have carcinogenic effects in OC, whereas IRF6 has not been reported in cancer." (PMID 38493179, 2024). "In CLDN3-positive cancer cells, h4G3 showed dose-dependent ADCC according to the level of CLDN3 expression through NK-92MI-CD16a cells, and there was no ADCC in CLDN3-negative cancer cells." (PMID 31905631, 2019). "To provide further evidence that the loss of E-cadherin and the gain of N-cadherin and Twist expression occurred as a direct result of the claudin status, we examined the effect of expressing CLDN3 and CLDN4 in the human cancer cell line HEY that does not express endogenous CLDN3 or CLDN4." (PMID 23805314, 2013). "In contrast, control HCC cells without endogenous CLDN3 displayed a spindle shape, fibroblast-like mesenchymal morphology, and pronounced cellular scattering in monolayer culture, suggesting the inactivation of CLDN3 in HCC might be related to EMT and cancer invasion/metastasis." (PMID 25277196, 2014).
infection (24 papers, 2005 to 2025). The state of being infected such as from the introduction of a foreign agent such as serum, vaccine, antigenic substance or organism. "Any loss of tight junction proteins (i.e., claudin-3), due to cell death or internalization via endocytosis in response to infection would be indicative of a loss of mucosal integrity." (PMID 32119719, 2020). "Specifically, ZO-1 expression decreased significantly early in infection (at 1 dpi), whereas occludin and claudin-3 levels significantly declined from 3 dpi, reaching their nadir at 7 dpi." (PMID 39799330, 2025). "Throughout the infection course, consistent inhibition of CLDN3 expression and enhancement of miR-181a expression were determined in LMIV-infected LMB-L cells." (PMID 39459923, 2024). "During T. spiralis infection, the expression of the gut epithelial TJ proteins occludin and claudin-3 was found to be downregulated beginning at 2 days post-infection, whereas claudin-2 was overexpressed." (PMID 35255974, 2022). "It has also been shown that claudin-1 and claudin-3 relocate from the membrane into the cell cytoplasm following infection with certain pathogens." (PMID 34867313, 2021). "The mRNA levels of claudin-1, claudin-3, claudin-7, claudin-11, occludin and ZO-1 were all downregulated in the case of infection with A. hydrophila (P < 0.05)." (PMID 34220849, 2021). "As assayed by immunofluorescence staining, CR infection led to a clearly disorganized distribution of claudin-3 on colon tissue sections derived from Il22-/- mice infected with wild-type CR, compared to PBS control, at 7 dpi." (PMID 31251784, 2019). "As shown, claudin-2 and claudin-3 proteins were expressed in the OE-129WT cells, and their expression levels either remained steady or were increased late during infection, while claudin-1 protein expression appeared to be diminished after the 20hr time-point." (PMID 30625140, 2019). "A cooperative effect between E. faecium supplementation and NE infection was noted for CLDN-3 protein expression (P < 0.05)." (PMID 31311959, 2019). "As expected, following infection, the expression of claudin 3 was dramatically reduced in MLKL−/− epithelium." (PMID 29456533, 2018). "In addition, the expression of p-p38 and p-p65 was decreased, and the expression of Occludin and Claudin-3 was increased after inhibition of calcium signalling during infection with S. maltophilia in MMECs." (PMID 38124149, 2023). "Claudin-3 expression was strong at cell–cell junctions between small intestinal epithelial cells; however, the claudin-3 signal decreased and junctional staining became unclear after infection, suggesting disruption of the tight junctions." (PMID 37939119, 2023). "The protein levels of tight junction-related proteins (ZO-1, occludin and claudin 3) reached their peak level at 4 hpi and then decreased, while those of the transcriptional regulators (p38, PKCα and p65) up-regulated and maintained high levels post-infection." (PMID 36768530, 2023). "In contrast, ΔespF CR infection failed to cause the disorganized distribution of claudin-3 on colon tissue sections, although the attachment of ΔespF CR to colonic epithelium was identical to, if not higher than, that of wild-type CR." (PMID 31251784, 2019). "There was no significant impact on transcription of any of the claudin genes tested when IFN-β was added to OE-TLR3(-) cells 1hr before infection, except for the 36hr timepoint when claudin-3 transcription was significantly higher in the IFN-β pre-treated TLR3-deficient OE cells." (PMID 30625140, 2019). "We have previously prepared sublines of the human epithelial cell line 2008, designated as CLDN3KD and CLDN4KD, in which CLDN3 or CLDN4 was constitutively knocked down by infection with a lentivirus expressing an shRNAi targeting to one or the other of these two claudins." (PMID 23805314, 2013).